TULP4 (TUB like protein 4)
Description:
May be a substrate-recognition component of a SCF-like ECS (Elongin-Cullin-SOCS-box protein) E3 ubiquitin ligase complex which mediates the ubiquitination and subsequent proteasomal degradation of target proteins.
Synonyms: KIAA1397; TUSP
Tractability: PROTAC: ubiquitination databases record sites on it; its protein half-life has been measured.
Gene: Protein-coding gene on chromosome 6 (158,232,236 to 158,511,828, forward strand). Ensembl gene ENSG00000130338.
Subcellular location: Cytoplasm
Subcellular location (Human Protein Atlas): Principal piece; Acrosome
Pathways (Reactome):
Metabolism of proteins: Neddylation
Gene Ontology:
Biological process: protein ubiquitination
Cellular component: cytoplasm; cytosol
Genetic constraint (gnomAD): Loss-of-function variants: 16 observed, 124.32 expected, observed/expected ratio (o/e) 0.13, 90% interval 0.086 to 0.19. The upper end of that interval is the gene's LOEUF score, 0.19, which puts it in group 1 of 6, group 1 being the genes least tolerant of losing a copy. Missense variants: 1,805 observed, 2,045.7 expected, observed/expected ratio (o/e) 0.88, 90% interval 0.85 to 0.92. Synonymous variants: 965 observed, 848.32 expected, observed/expected ratio (o/e) 1.14, 90% interval 1.08 to 1.2.
Homologues: Orthologues: chimpanzee TULP4 (99% identical), macaque TULP4 (97% identical), mouse Tulp4 (94% identical), rat Tulp4 (94% identical), guinea pig TULP4 (93% identical), dog TULP4 (92% identical), rabbit TULP4 (91% identical), tropical clawed frog tulp4 (82% identical), zebrafish tulp4a (72% identical), zebrafish tulp4b (70% identical), Drosophila melanogaster Tusp (33% identical), Caenorhabditis elegans tub-2 (21% identical). Paralogues in human: WDR35 (16% identical), TUB (8% identical), TULP3 (7% identical), TULP1 (7% identical), TULP2 (6% identical).
Diseases named in the same sentence as TULP4 in open-access papers:
TULP4 is named in the same sentence as 8 diseases in open-access papers, as found by Europe PMC text mining. Sharing a sentence is not in itself a finding about the gene and the disease. The quoted sentences say what the papers report.
Alzheimer disease (1 paper, 2021). A progressive, neurodegenerative disease characterized by loss of function and death of nerve cells in several areas of the brain leading to loss of cognitive function such as memory and language. "Introns derived from the Tulp4 gene can be cyclized to form circTulp4, which can interact with U1 snRNP and RNA polymerase II to regulate the transcription of its parental gene, Tulp4, thus participate in the development of Alzheimer’s disease (AD)." (PMID 35116058, 2021).
diabetes (1 paper, 2020). "However, the circ-Tulp4 level was not significantly affected in Min6 cells treated with diabetes-associated cytokine cocktails." (PMID 33064661, 2020).
orofacial cleft (1 paper, 2020). A disorder of facial skeleton that is characterized by cleft lip and/or cleft palate that result in feeding, speech and hearing problems caused by failures during development. "TULP4 has been implicated in the formation of orofacial clefts and is a body height GWAS locus." (PMID 32216834, 2020).
systemic sclerosis (1 paper, 2020). A chronic disorder, possibly autoimmune, marked by excessive production of collagen which results in hardening and thickening of body tissues. "However, the genes harboring intronic SNPs, ALK (rs4575680), EPHA3 (rs1512909), and TULP4, also known as TUSP (rs341137), have been implicated in CVD-related traits, such as blood pressure, arterial fibrillation, and systemic sclerosis." (PMID 33374401, 2020).
cancer (3 papers, 2021 to 2023). A tumor composed of atypical neoplastic, often pleomorphic cells that invade other tissues. "The role of TULP4, MKLN1, and ZNF532 in cancer is largely unknown." (PMID 35078526, 2022).
TULP4 also shares sentences with these, for which no sentence is quoted: infection (1 paper); non-Hodgkin lymphoma (1); pancreatic ductal adenocarcinoma (1).